RPS17 (ribosomal protein S17)
Description:
Component of the small ribosomal subunit. The ribosome is a large ribonucleoprotein complex responsible for the synthesis of proteins in the cell. Part of the small subunit (SSU) processome, first precursor of the small eukaryotic ribosomal subunit. During the assembly of the SSU processome in the nucleolus, many ribosome biogenesis factors, an RNA chaperone and ribosomal proteins associate with the nascent pre-rRNA and work in concert to generate RNA folding, modifications, rearrangements and cleavage as well as targeted degradation of pre-ribosomal RNA by the RNA exosome.
Synonyms: RPS17L; RPS17L1; RPS17L2; MGC72007; S17; eS17; DBA4
Tractability: Small molecule: an approved drug acts on it; a structure with a bound ligand is known; a high-quality ligand is known. PROTAC: UniProt records ubiquitination sites on it; ubiquitination databases record sites on it; its protein half-life has been measured; a small molecule that binds it is known. Other modalities: a drug acting on it is in phase 2 or 3 trials.
Target class: Other cytosolic protein
Gene: Protein-coding gene on chromosome 15 (82,536,748 to 82,540,535, reverse strand). Ensembl gene ENSG00000182774.
Subcellular location: Cytoplasm; Nucleus, nucleolus
Subcellular location (Human Protein Atlas): Cytosol; Endoplasmic reticulum; Nucleoli
Pathways (Reactome):
Metabolism of proteins: Eukaryotic Translation Termination; Formation of a pool of free 40S subunits; Formation of the ternary complex, and subsequently, the 43S complex; GTP hydrolysis and joining of the 60S ribosomal subunit; L13a-mediated translational silencing of Ceruloplasmin expression; PELO:HBS1L and ABCE1 dissociate a ribosome on a non-stop mRNA; Peptide chain elongation; Ribosomal scanning and start codon recognition; SRP-dependent cotranslational protein targeting to membrane; Translation initiation complex formation; ZNF598 and the Ribosome-associated Quality Trigger (RQT) complex dissociate a ribosome stalled on a no-go mRNA
Disease: SARS-CoV-1 modulates host translation machinery; SARS-CoV-2 modulates host translation machinery; Viral mRNA Translation
Metabolism of RNA: Major pathway of rRNA processing in the nucleolus and cytosol; Nonsense Mediated Decay (NMD) enhanced by the Exon Junction Complex (EJC); Nonsense Mediated Decay (NMD) independent of the Exon Junction Complex (EJC)
Cellular responses to stimuli: Response of EIF2AK4 (GCN2) to amino acid deficiency
Developmental Biology: Regulation of expression of SLITs and ROBOs
Metabolism: Selenocysteine synthesis
Gene Ontology:
Molecular function: RNA binding; structural constituent of ribosome
Biological process: erythrocyte homeostasis; ribosomal small subunit biogenesis; rRNA processing; cytoplasmic translation; translation; translational initiation
Cellular component: cytoplasm; cytosolic ribosome; cytosolic small ribosomal subunit; focal adhesion; membrane; small-subunit processome; cytosol; nucleoplasm; ribosome; nucleolus; synapse
Genetic constraint (gnomAD): Loss-of-function variants: 0 observed, 17.56 expected, observed/expected ratio (o/e) 0, 90% interval 0 to 0.17. The upper end of that interval is the gene's LOEUF score, 0.17, which puts it in group 1 of 6, group 1 being the genes least tolerant of losing a copy. Missense variants: 68 observed, 187.87 expected, observed/expected ratio (o/e) 0.36, 90% interval 0.3 to 0.44. Synonymous variants: 75 observed, 66.66 expected, observed/expected ratio (o/e) 1.13, 90% interval 0.93 to 1.36.
Homologues: Orthologues: macaque RPS17 (100% identical), guinea pig Rps17 (99% identical), mouse Rps17 (99% identical), pig RPS17 (99% identical), rabbit RPS17 (99% identical), rat LOC100365810 (99% identical), rat LOC100362366 (98% identical), rat Rps17l2 (98% identical), zebrafish RPS17 (97% identical), tropical clawed frog rps17 (84% identical), Drosophila melanogaster RpS17 (75% identical), rabbit RPS17 (68% identical), and 1 more.
Diseases named in the same sentence as RPS17 in open-access papers:
RPS17 is named in the same sentence as 37 diseases in open-access papers, as found by Europe PMC text mining. Sharing a sentence is not in itself a finding about the gene and the disease. The quoted sentences say what the papers report.
Diamond-Blackfan anemia (15 papers, 2009 to 2025). A congenital aregenerative and often macrocytic anemia with erythroblastopenia. "Mutations of RPS19, as well as of two other ribosomal proteins, RPS24 and RPS17, have been linked to the rare congenital disease Diamond-Blackfan Anemia." (PMID 28680364, 2016). "Four RP genes, RPS19 RPS24, RPS17, and RPL35a are known to be mutated in Diamond-Blackfan anemia (DBA; MIM 105650), a congenital erthyroid aplasia characterized by macrocytic anemia." (PMID 19129914, 2009). "Additionally, RPS17 encodes a protein subunit of ribosome, which is recognized as causative for Diamond-Blackfan anemia, but it has frequently coincided with syndromic cryptorchidism as well." (PMID 30093884, 2018). "RPS17 mutation leads to impaired translation, which may cause Diamond-Blackfan anemia." (PMID 36777722, 2023). "RPS17 along with RPS19 and RPS24 have been linked to diseases in humans including Diamond-Blackfan Anemia, an erythroid aplasia resulting in a deficiency of red blood cell precursors in the bone marrow." (PMID 25853866, 2015). "For example, the localization of human ribosomal protein S17 in the nucleoli may be related to Diamond-Blackfan Anemia (DBA)." (PMID 33670294, 2021). "Notably, ribosomal subunits were either unchanged or decreased, and several genes implicated in Diamond-Blackfan Anemia (TSR2 ribosome maturation factor [TSR2], RPS26, RPS17) clustered in the group showing the largest decreases in translation efficiency." (PMID 33137094, 2020). "Human ribosomal protein S17 (RPS17) is mutated in Diamond-Blackfan Anemia (DBA), a bone marrow disorder that fails to produce sufficient red blood cells leading to anemia." (PMID 25853866, 2015). "Further, mutations in several ribosomal protein (RP) genes, such as RPS19, RPL5, RPL11, RPL35A, RPS10, RPS17, and RPS24, cause Diamond-Blackfan anemia (DBA)." (PMID 38820160, 2024). "In humans, mutations in RPs have been implicated in hematopoetic disorders, most notably Diamond-Blackfan anemia (DBA), which has been attributed to mutations in RPS19, RPS26, RPS24, RPS17, RPS10, RPS7, RPL35a, RPL26, RPL11, and RPL5." (PMID 23382688, 2013). "The most well characterized is Diamond Blackfan anemia (DBA), which results from haploinsufficiencies in several different RP genes (RPS24/eS24, RPS17/eS17, RPL35A/eL33, RPL5/uL18, RPL11/uL5, RPS7/eS7, RPL36/eL36, RPS15/uS19, RPS27A/eS31) and RPS19/eS19, which is mutated in 25% of patients." (PMID 33565275, 2021).
schizophrenia (3 papers, 2020 to 2023). A major psychotic disorder characterized by abnormalities in the perception or expression of reality. "Patients 2's duplication encompasses 11 OMIM genes, of which RPS17, HOMER2, and ADAMTS3 have already been described as schizophrenia-associated genes in the literature." (PMID 33510659, 2020). "RPS17 also demonstrated strong evidence for colocalization between the TWAS weights and schizophrenia in the PsychENCODE cortical dataset (PPH4 = 0.953), which was also seen for FADS1 and bipolar disorder (PPH4 = 0.95)." (PMID 36055211, 2022).
Arthritis (1 paper, 2025). Inflammation of a joint. "Based on RPS17-overexpressed monocytic OCPs, we designed a safe and effective cytotherapy regimen that effectively improves arthritis, joint destruction and ossification while avoiding further reduction in bone mass and obvious side effects." (PMID 41345114, 2025). "RPS17-overexpressed cells also had stronger abilities than control cells in alleviating ankle-joint swelling and decreasing arthritis scores." (PMID 41345114, 2025).
choroidal melanoma (1 paper, 2025). Malignant tumor of melanocytes of the choroid. "have highlighted substantial RPS17 expression in primary choroidal melanoma tissues and liver metastases, suggesting its potential role in tumor pathology." (PMID 41127012, 2025).
colorectal cancer (1 paper, 2025). A primary or metastatic malignant neoplasm that affects the colon or rectum. "Previous studies have confirmed that elevated expression of RPS17 in colorectal cancer tissues is associated with poor prognosis in patients." (PMID 41127012, 2025). "The expression levels of TPM2, RPS17, and TNNT1 progressively increased during the progression and metastasis of colorectal cancer (CRC); in contrast, SPINK4 expression initially rose before sharply declining." (PMID 41127012, 2025). "During the metastasis process, we observed significant increases in the expression of the TPM2, RPS17, and TNNT1 genes in colorectal cancer epithelial cells, while SPINK4 expression was notably reduced." (PMID 41127012, 2025). "The expression levels of TPM2, RPS17, and TNNT1 were significantly elevated, while SPINK4 expression was reduced in the epithelial cells of colorectal cancer with liver metastasis." (PMID 41127012, 2025). "During liver metastasis in colorectal cancer, the expression levels of TPM2, RPS17, and TNNT1 were significantly elevated, SPINK4 expression was reduced in the epithelial cells." (PMID 41127012, 2025).
deafness (1 paper, 2014). An inherited or acquired condition characterized by the complete loss of the ability to hear from one or both ears. "Of them, 9 deafness genes expressed more in the apical turn (Pou4f3, Slc17a8, Tmc1, Crym, Otof, Ush1c, Pcdh15, Slc26a5, and Lhfpl5) and six were internal controls (Gapdh, Actb, Rps17, Rpl30, Atp6, and Ipo8)." (PMID 24676347, 2014).
depression (1 paper, 2022). "Specifically, there was an association between the SZ CACNA1C PES and increased odds of depression, while the SZ RPS17 network PES was associated with increased odds of self-reported OCD." (PMID 36055211, 2022).
macrocytic anemia (1 paper, 2024). Anemia that is characterized by increased red blood cell volume.
ovarian endometrioid adenocarcinoma (1 paper, 2025). An endometrioid adenocarcinoma arising from the ovary. "In another study, a comparison of five healthy control ovarian samples with three ovarian endometrioid adenocarcinoma samples demonstrated the least variation in levels of PPIA, RPL37A (Ribosomal protein L37a), and RPS17 (Ribosomal protein S17) among the investigated HKGs." (PMID 40943534, 2025).
thymoma (1 paper, 2021). A neoplasm arising from the epithelial cells of the thymus. "The overall survival data from GEPIA2 demonstrated that low levels of FAU, RPS17, and RPS 24 were significantly associated with shorter survival, while high CCL4 was significantly associated with shorter survival in thymoma patients." (PMID 34760386, 2021).
virus infection (1 paper, 2015). "Understanding the biological function of RPS17 is critical for elucidating its role in virus infection and DBA disease processes." (PMID 25853866, 2015).
α-synucleinopathy (1 paper, 2016). "Further detailed studies will be required to precisely identify the role of Rps17 related to the findings of the current study and their relevance to the different vulnerability to oligodendroglial α-synucleinopathy in striatum and SN." (PMID 26962858, 2016).
cancer (8 papers, 2016 to 2024). A tumor composed of atypical neoplastic, often pleomorphic cells that invade other tissues. "Our findings indicate that tumors with elevated expression levels of HEYL, RPS17, and JDP2 are associated with a poorer prognosis for cancer patients." (PMID 39676867, 2024). "DBA variants in patients with cancer/MDS refer mainly to RPS19, RPL35A, RPL11, RPL5, RPS17, and GATA1 genes (18%, 13%, 10%, 5%, 3%, and 3%, respectively; 49% unknown)." (PMID 38002903, 2023).
infection (4 papers, 2017 to 2023). The state of being infected such as from the introduction of a foreign agent such as serum, vaccine, antigenic substance or organism. "This 174-nt (58-aa) insertion derived from ribosomal protein S17 (RPS17) RNA was selected in cell culture after infection with a stool sample from a patient with chronic hepatitis E." (PMID 37112849, 2023). "Levels of Stat‐A and RpS17 were unaffected by a larval infection." (PMID 31161020, 2019). "Transcription of ecdysteroid biosynthesis genes and, as expected, RPS17 was not regulated by infection in any age group." (PMID 28764812, 2017).
tumor (2 papers, 2021 to 2025). "Additionally, the upregulation of RPS17 correlates with a decrease in the tumor microenvironment (TME) score, suggesting a potential link between RPS17 expression and TME heterogeneity." (PMID 41127012, 2025). "Interestingly, RL30, RPS17, ROAA, S10A6 and TRHY were deregulated in IDH-wild type GBM versus non-tumour samples in the TCGA database." (PMID 34316702, 2021).
RPS17 also shares sentences with these, for which no sentence is quoted: anemia (2 papers); ankylosing spondylitis (1); bipolar disorder (1); Bloom syndrome (1); Bochdalek hernia (1); bone marrow disorder (1); Bowen-Conradi syndrome (1); co-infection (1); cognitive deficits (1); congenital anemia (1); cryptorchidism (1); hepatoma (1); hereditary thrombocytopenia (1); Lynch syndrome (1); melanoma (1); pancreatic cancers (1); prostate carcinoma (1); rapadilino syndrome (1); tauopathies (1); Treacher-Collins syndrome (1); uterine diseases (1); Werner syndrome (1).